SIGMAR1 (sigma non-opioid intracellular receptor 1)
Description:
Functions in lipid transport from the endoplasmic reticulum and is involved in a wide array of cellular functions probably through regulation of the biogenesis of lipid microdomains at the plasma membrane. Involved in the regulation of different receptors it plays a role in BDNF signaling and EGF signaling. Also regulates ion channels like the potassium channel and could modulate neurotransmitter release. Plays a role in calcium signaling through modulation together with ANK2 of the ITP3R-dependent calcium efflux at the endoplasmic reticulum. Plays a role in several other cell functions including proliferation, survival and death. Originally identified for its ability to bind various psychoactive drugs it is involved in learning processes, memory and mood alteration. Necessary for proper mitochondrial axonal transport in motor neurons, in particular the retrograde movement of mitochondria. Plays a role in protecting cells against oxidative stress-induced cell death via its interaction with RNF112 (By similarity).
Synonyms: SR-BP; SIG-1R; Sigma1R; hSigmaR1; OPRS1; SRBP; SR-BP1; ALS16; DSMA2; HMNR2
Tractability: Small molecule: an approved drug acts on it; a structure with a bound ligand is known; a high-quality ligand is known; it belongs to a druggable protein family. Antibody: UniProt places it where antibodies can reach, with high confidence; UniProt predicts a signal peptide or a membrane-spanning region; its Gene Ontology location is reachable by antibodies, with medium confidence. PROTAC: ubiquitination databases record sites on it; its protein half-life has been measured; a small molecule that binds it is known.
Target class: Membrane receptor
Chemical probes: E1R, IFENPRODIL, NE-100
Safety:
Unwanted effects reported when the protein is acted on. In parentheses: how it was acted on, where the effect was seen, and who reports it.
decreased anxiety (activation, acute dosing; nervous system; source: Lynch et al. (2017))
decreased convulsions (activation, acute dosing; nervous system; source: Lynch et al. (2017))
decreased pain (inhibition, acute dosing; nervous system; source: Lynch et al. (2017))
drug abuse/dependence (activation, acute dosing; nervous system; source: Lynch et al. (2017))
hallucinations (activation, acute dosing; nervous system; source: Lynch et al. (2017))
increased memory (activation, acute dosing; nervous system; source: Lynch et al. (2017))
Gene: Protein-coding gene on chromosome 9 (34,634,720 to 34,637,844, reverse strand). Ensembl gene ENSG00000147955.
Subcellular location: Nucleus inner membrane; Nucleus outer membrane; Nucleus envelope; Cytoplasmic vesicle; Endoplasmic reticulum membrane; Membrane; Lipid droplet; Cell junction; Cell membrane; Cell projection, growth cone; Postsynaptic density membrane
Pathways (Reactome):
Disease: Potential therapeutics for SARS
Gene Ontology:
Molecular function: protein binding; signaling receptor activity; G protein-coupled opioid receptor activity
Biological process: protein homotrimerization; regulation of neuron apoptotic process; regulation of response to endoplasmic reticulum stress; conditioned place preference; cyclooxygenase pathway; G protein-coupled opioid receptor signaling pathway; negative regulation of neuron apoptotic process; negative regulation of nitric oxide biosynthetic process; negative regulation of response to endoplasmic reticulum stress; nervous system development; positive regulation of protein localization to nucleolus; prostaglandin biosynthetic process; regulation of postsynapse assembly; response to alcohol; response to methamphetamine hydrochloride
Cellular component: cytoplasmic vesicle; endoplasmic reticulum; endoplasmic reticulum membrane; membrane; nuclear envelope; nuclear inner membrane; nuclear outer membrane; plasma membrane; postsynaptic density; postsynaptic density membrane; cytosol; lipid droplet; anchoring junction; axon; cytoplasm; dendrite; glutamatergic synapse; growth cone; neuronal cell body; postsynapse
Genetic constraint (gnomAD): Loss-of-function variants: 18 observed, 20.75 expected, observed/expected ratio (o/e) 0.87, 90% interval 0.6 to 1.29. The upper end of that interval is the gene's LOEUF score, 1.29, which puts it in group 5 of 6, group 1 being the genes least tolerant of losing a copy. Missense variants: 249 observed, 266.23 expected, observed/expected ratio (o/e) 0.94, 90% interval 0.84 to 1.04. Synonymous variants: 125 observed, 113.49 expected, observed/expected ratio (o/e) 1.1, 90% interval 0.95 to 1.28.
Homologues: Orthologues: chimpanzee SIGMAR1 (100% identical), macaque SIGMAR1 (100% identical), dog SIGMAR1 (98% identical), rabbit SIGMAR1 (96% identical), pig SIGMAR1 (95% identical), guinea pig SIGMAR1 (95% identical), rat Sigmar1 (94% identical), mouse Sigmar1 (90% identical), tropical clawed frog sigmar1 (65% identical), zebrafish sigmar1 (64% identical), Caenorhabditis elegans W08F4.3 (21% identical).
Diseases named in the same sentence as SIGMAR1 in open-access papers:
SIGMAR1 is named in the same sentence as 155 diseases in open-access papers, as found by Europe PMC text mining. Sharing a sentence is not in itself a finding about the gene and the disease. The quoted sentences say what the papers report.
Parkinson disease (26 papers, 2013 to 2025). A progressive degenerative disorder of the central nervous system characterized by loss of dopamine producing neurons in the substantia nigra and the presence of Lewy bodies in the substantia nigra and locus coeruleus. "Since the discovery of Sigmar1, alterations in the it’s function have been reported to associate with the development of neurodegenerative diseases, including Alzheimer’s disease (AD), Parkinson’s disease (PD), and Huntington’s disease (HD)." (PMID 34305655, 2021). "Accumulating study suggested that the induction of SIGMAR1 expression exhibited outstanding neuroprotective effects in Parkinson’s disease and Alzheimer’s disease." (PMID 35412431, 2022). "The converse was also true when using dopaminergic neurons where Sigmar1 activation by agonists (PRE-084) rescued the defects in mitophagy clearance in Parkinson’s disease in a PINK/Parkin dependent pathway." (PMID 34305655, 2021). "In addition, Sigmar1’s chaperone activity has been reported to degrade intranuclear inclusions and provide neuroprotection in Huntington’s disease, Alzheimer’s disease, and Parkinson’s disease." (PMID 34305655, 2021). "Pridopidine demonstrates neuroprotective effects, which are exquisitely mediated by activation of the SIGMAR1 in models of several neurological diseases including ALS, Huntington disease, Alzheimer disease and Parkinson disease." (PMID 35507432, 2023). "While mutations in the SIGMAR1 gene have been reported in association with ALS, with or without frontotemporal dementia or juvenile ALS, no instances of this mutation in the ALS–Parkinson’s disease (PD) complex have been described until now." (PMID 37780700, 2023).
amyotrophic lateral sclerosis (25 papers, 2013 to 2025). Amyotrophic lateral sclerosis (ALS) is a neurodegenerative disease characterized by progressive muscular paralysis reflecting degeneration of motor neurons in the primary motor cortex, corticospinal tracts, brainstem and spinal cord. "Familial amyotrophic lateral sclerosis (ALS) patients have been reported to exhibit the missense mutation c.304G>C in the SIGMAR1 gene." (PMID 37047338, 2023). "This case report aims to raise awareness among physicians regarding atypical phenotypes of amyotrophic lateral sclerosis and to encourage further research on the factors leading to SIGMAR1 mutations in patients." (PMID 37780700, 2023). "A recent biophysical study suggested that the E102Q mutation associated with familial amyotrophic lateral sclerosis (ALS) disrupts the higher-order oligomerization of SigmaR1, thus leading to its dysfunction." (PMID 37444574, 2023). "Notably, the SIGMAR1 gene is especially contentious due to significant phenotypic overlap; mutations within SIGMAR1 are frequently associated with conditions that exhibit clinical features reminiscent of Amyotrophic Lateral Sclerosis (ALS)." (PMID 40309037, 2025). "Different disorders are associated with known mutations in human SIGMAR1, including frontotemporal lobar degeneration (FTLD) and motor neuron diseases such as autosomal recessive distal hereditary motor neuropathy and juvenile amyotrophic lateral sclerosis (ALS)." (PMID 33020464, 2020).
depression (20 papers, 2014 to 2025). "The SIGMAR1 appears to play a central role in central nervous system (CNS) diseases since polymorphisms in the SIGMAR1 gene are associated with depression, schizophrenia and alcoholism as well as AD." (PMID 25261976, 2014). "However, a SIGMAR1 polymorphism (rs1800866) that results in a substitution from glutamine (CAG) to proline (CCG) has been associated with an increased risk of major depressive disorder in the Japanese population and bipolar disorder in the Korean population." (PMID 35884876, 2022). "Sigmar1 has a prominent effect on the psychiatric behaviors in mice, including depression and anxiety." (PMID 34305655, 2021). "A recent study in MI mice showed that a decreased brain Sigmar1 played a vital role in the coexistence of increased HF via sympathoexcitation and mental disorders, such as depression or cognitive impairment." (PMID 34305655, 2021). "Genome-wide association studies in the general population of humans have not found a link between SIGMAR1 and major depressive disorder." (PMID 35884876, 2022). "Sigmar1 has a significant therapeutic potential to treat the cardiovascular disease as reflected by two Sigmar1 ligands already in clinical trials: cutamesine (SA4503) for ischemic stroke (Phase II) and sertraline for depression in patients with heart failure (SADHART-CHF)." (PMID 34305655, 2021).
Stroke (16 papers, 2012 to 2026). Sudden impairment of blood flow to a part of the brain due to occlusion or rupture of an artery to the brain. "Also, an association (OR = 0.65; 95% CI: 0.46-0.91; P = 0.012) between the SIGMAR1 encoding rs12001648 and medium-severe stroke onset risk (NIHSS ≥ 8) was found." (PMID 25261976, 2014). "With this background we aimed to investigate whether polymorphisms in the APOD and SIGMAR1 genes influence stroke severity as well as functional outcome in patients suffering from IS." (PMID 25261976, 2014). "Hence, a mutation could affect trafficking of SIGMAR1 associated processes, which have been implicated in rodent models of stroke." (PMID 25261976, 2014). "In this first attempt to study if stroke repair mechanisms linked to certain regions within the APOD and SIGMAR1 genes may also affect recovery from stroke and severity of stroke, we performed a candidate gene study including twelve SNPs from these two genetic regions." (PMID 25261976, 2014). "SIGMAR1 primarily functions in physiological and pathophysiological processes of the CNS, such as pain, memory, neurodegenerative diseases, stroke, and addiction." (PMID 36435867, 2022). "Similarly, GSE35338 dataset revealed a significant reduction in Sigmar1 expression in astrocytes in the MCAO group on day 3 post-stroke compared to that of the sham group." (PMID 41356802, 2026). "However; we could not find any association between the SIGMAR1 polymorphisms and stroke risk, severity or recovery." (PMID 25261976, 2014). "Studies have also shown that treatment with Sigmar1 agonists (such PRE-084) reduced infarct volume, neurological deficits, levels of pro-inflammatory cytokines, and enhanced the actions of anti-inflammatory cytokines after embolic stroke in rats." (PMID 34305655, 2021).
distal hereditary motor neuropathy (15 papers, 2016 to 2025). "Several publications have associated truncations/deletions in Sigmar1 with the development of distal hereditary motor neuropathies (MIM #605726)." (PMID 35628876, 2022). "Mutations in SIGMAR1 are associated with distal hereditary motor neuropathy." (PMID 33810178, 2021). "Several truncations/deletions or point mutations in SIGMAR1 generated distal hereditary motor neuropathy, while juvenile cases of ALS were associated with a missense mutation (c.304G>C, p.E102Q) and a frameshift mutation (c.283dupC, p.L95fs) in the SIGMAR1 gene sequence." (PMID 34681705, 2021). "These clinical skeletal muscle phenotypes, all of which were observed in Sigmar1 mutation-bearing patients, have also been observed in patients with distal hereditary motor neuropathy (dHMN)." (PMID 34305655, 2021). "SIGMAR1 mutations have also been associated with distal hereditary motor neuropathy (dHMN)." (PMID 34946884, 2021).
breast carcinoma (11 papers, 2003 to 2025). "In summary, SigmaR1 is a small receptor with variable cellular functions, and is associated with a wide range of human diseases, including breast cancer." (PMID 37444574, 2023). "Several studies showed that SigmaR1 is highly expressed both at the gene and protein levels in breast cancer patient tissues and is associated with a worse prognosis and poor survival outcomes." (PMID 37444574, 2023). "SigmaR1 is a receptor implicated in certain types of breast cancer and represents a promising target for a new generation of personalized treatments." (PMID 37444574, 2023). "Analyzing nearly 5000 patients with breast cancer revealed that the increased expression of both SigmaR1 and Orai1 channels was linked to poorer overall survival rates." (PMID 37444574, 2023). "Curiously, in the last decade the potential function of SIGMAR1 in cancer has gained increasing interest as a potential new biomarker, as previously demonstrated in breast cancer, colorectal cancer, and prostate cancer." (PMID 39595926, 2024). "The overexpression of SIGMAR1 has also been demonstrated in breast cancer and colorectal cancer; this is consistent with our results." (PMID 39595926, 2024). "For instance, in breast cancer, SIGMAR1 has been shown to promote cell proliferation and survival, while in prostate cancer, its expression correlates with increased tumor growth and resistance to apoptosis." (PMID 39595926, 2024). "This article reviews the current knowledge about SigmaR1 in breast cancer biology and potential treatment and proposes a new model as to how SigmaR1 operates within the cell in order to devise new effective ways for utilizing it in the clinic." (PMID 37444574, 2023). "Mounting evidence has presented Sigma receptor 1 (SigmaR1) as a potential target in the diagnosis and treatment of breast cancer." (PMID 37444574, 2023). "SigmaR1 has been found to be upregulated in a number of cancers including lung cancer, breast cancer, glioblastoma, esophageal cancer, pancreatic cancer, prostate cancer, and liver cancer." (PMID 37444574, 2023). "Due to its relationship with SigmaR1 and the role it plays in various cancers, including breast cancer, intensive research has been conducted into the use of Haldol and its analogs as anticancer therapeutics." (PMID 37444574, 2023). "Increased levels of SigmaR1 were found in breast cancer tissue samples and were correlated with tumor grade." (PMID 37444574, 2023). "Despite the unclear function and the complex cellular role, active current research has been directed to investigating the potential of targeting SigmaR1 in breast cancer, particularly the TNBC subtype that lacks biomarkers." (PMID 37444574, 2023). "The role of Sigmar1 has been widely studied in different types of cancers, including prostate cancer, colorectal cancer, breast cancer, and hepatocarcinoma." (PMID 34305655, 2021). "Clinical studies have shown high levels of Sigmar1 in tumor tissues from breast cancer patients and has been proposed to be used as a clinical marker of breast cancer." (PMID 34305655, 2021). "Similar results were observed in experiments carried out in vitro and in vivo (rodent models), where Sigmar1 was essential for the growth of prostate cancer, breast cancer, and colorectal cancer cells." (PMID 34305655, 2021). "Additionally, nothing thus far has been shown about the likely effects of protein post-translational modification on SigmaR1’s role in breast cancer." (PMID 37444574, 2023). "Similarly, SigmaR1 has been a target of the search for treatment in other types of cancer that can be translated to treating breast cancer." (PMID 37444574, 2023). "Thus, much research lies ahead to mechanistically utilize the SigmaR1-IQGAP1 axis as a precision target in treating breast cancer." (PMID 37444574, 2023).
breast carcinoma (continued). "Additionally, Sigmar1 inhibition altered calcium homeostasis increased apoptotic cell death, and inhibit cancer cell proliferation and migration in breast cancer and colorectal cancer cells." (PMID 34305655, 2021). "Biochemical and confocal microscopic studies showed that SigmaR1 physically binds to SK3 channels and that inhibiting SigmaR1 reduced SK3 and Orai1 expression in breast cancer cells." (PMID 37444574, 2023).
cognitive deficits (10 papers, 2019 to 2025). "Like SigmaR1, IQGAP1 promotes ROS via Rac1 GTPase, and studies in mouse models have implicated IQGAP1 in memory and cognitive deficits." (PMID 37444574, 2023).
COVID-19 (10 papers, 2020 to 2024). A disease caused by infection with severe acute respiratory syndrome coronavirus 2. "One such example is the interaction between Nsp6 and Sigma-1 (encoded by SIGMAR1 gene), which led to the identification, among others, of Fluphenazine, Chlorpromazine and Haloperidol, proposed as potential drug candidates for repurposing against COVID-19." (PMID 33430309, 2021). "Both Sigmar1 agonist (fluvoxamine) and antagonist (haloperidol) underwent clinical trial for possible therapy in patients with COVID-19." (PMID 34305655, 2021). "Further studies of the role of Sigmar1 in COVID-19 have suggested a functional host-dependency factor for SARS-CoV-2; the absence of Sigmar1 by knockdown reduced the replication of SARS-CoV-2 protein, delaying disease progression and presenting Sigmar1 as an attractive therapeutic target." (PMID 34305655, 2021). "The interaction map for SARS-CoV-2 protein reveals Sigmar1 interaction with Nsp6 (SARS-CoV-2 viral protein) and proposed Sigmar1 ligands as a possible therapeutic target for COVID-19." (PMID 34305655, 2021). "NSP1 hoSPIs included the nonopioid sigma receptor SIGMAR1, which was recently identified as host-dependency factor for SARS-CoV-2 infection and represents a potential drug target for treatment of COVID-19." (PMID 34909432, 2021).
Huntington disease (9 papers, 2016 to 2024). Huntington disease (HD) is a rare neurodegenerative disorder of the central nervous system characterized by unwanted choreatic movements, behavioral and psychiatric disturbances and dementia. "Overexpression of SIGMAR1 or POM121, or treatment with the highly selective and potent SIGMAR1 agonist pridopidine, currently in phase 2/3 clinical trials for ALS and Huntington disease, rescues all of these deficits." (PMID 35507432, 2023).